CXCR4 (C-X-C motif chemokine receptor 4)
Diseases named in the same sentence as CXCR4 in open-access papers (continued):
Sharing a sentence is not in itself a finding about the gene and the disease.
cancer (continued). "The major interest in this chemokine as a potential target for cancer therapy flows from studies that mostly investigated the direct interaction between CXCL12 and CXCR4 on cancer cells." (PMID 34944943, 2021). "Potential mechanisms of resistance include down-regulation or internalization of surface CXCR4, heterogeneous expression in cancer cells resulting in incomplete targeting, and potential competition with locally increased CXCL12 concentrations." (PMID 32260318, 2020). "PDA cancer cells exhibit an extracellular complex that include CXCL12, the ligand for CXCR4, which is expressed by cancer associated fibroblasts (CAF)." (PMID 33584695, 2020). "CXCR4 is strongly expressed in various types of cancer cells, contributing to tumorigenesis and cancer progression, e.g., chemotaxis, invasion, angiogenesis, and cell proliferation." (PMID 33396481, 2020). "Cancer targeted nanoprobes were either adsorbed (AMD3100 targeting CXCR4 and Diadzein targeting Caveolin-1) or chemically crosslinked (folic acid targeting folate receptor) to the surface of the albumin nanocomposites." (PMID 33172421, 2020). "Nowadays, the relevance of the CXCL12/CXCR4 axis in cancers has been ascertained through the impact of the CXCR4 genomic landscape in clinical settings." (PMID 32260318, 2020). "CXCR4 signaling has been shown to be involved in the MAPK signaling pathway in cancer, mediating functions that include cell migration and survival." (PMID 32194542, 2020). "SDF-1/CXCR4 signaling also benefits cancer cells by elevating the cells ability to express and secrete matrix metalloproteinases (MMPs) such as MMP953." (PMID 32355198, 2020). "A series of efforts has been undertaken to investigate the prominent role of the CXCL12/CXCR4 axis in cancer progression of different cancer entities including both histologic subtypes of EC." (PMID 32560537, 2020). "CXCR4 is the most common chemokine receptor that is considered to be overexpressed in more than 23 different human cancers." (PMID 33092204, 2020). "The CXCR7/CXCR4 heterodimer can recruit nuclear β-arrestin 1 to enhance cancer cell migration and activate PI3K and MAPK pathways." (PMID 32260318, 2020). "In our research, the expression levels of CXCR members in distinct cancers were analyzed, and we found that CXCR4, CXCR6, and CXCR7 were highly expressed in ccRCC samples from ONCOMINE." (PMID 33324682, 2020). "Increasing evidence indicates a pivotal role for the CXCL12/CXCR4 axis in organ-specific metastasis of various cancers." (PMID 32079335, 2020). "In vivo studies demonstrated that activation of CXCL12/CXCR4 accelerates the recruitment of fibroblasts and facilitates cancer stromal formation." (PMID 33363463, 2020). "The abrogation of the CXCR4/CXCL12 axis results in reduced metastatic burden in a variety of mouse models of cancer." (PMID 32232002, 2020). "CXCR4 is one of several “chemokine” receptors expressed on malignant tumors (including GBM and PCNSL) and hematopoietic stem cells." (PMID 32239371, 2020). "This chemoresistance is thought to be mediated by Src and CXCR4 signaling, particularly because CXCR4 antibody treatment reduces the invasive ability of cancer cells." (PMID 33363463, 2020). "Given its pleiotropic functions, including its prominent role in inflammation, immune responses and cancer, the C-X-C chemokine receptor type 4 (CXCR4) has gained significant attention in recent years and has become a relevant target in drug development." (PMID 32784523, 2020). "The chemokine receptor CXCR4 is a G-protein-coupled receptor that plays an important role in the immune response and in the progression of many diseases, including cancer and HIV infection." (PMID 32610042, 2020). "Among them, CXC Cytokine Ligand 12 (CXCL12, formerly known as stromal cell-derived factor-1, SDF1) and CXC receptor 4 (CXCR4) comprise the CXCL12-CXCR4 axis, which is widely acknowledged as playing a vital role in cancer metastasis." (PMID 32538273, 2020).
cancer (continued). "In HCT116 and HT29 cells, CT/RT-CT induced a population of CD133+CXCR4+ cells, supposedly a stem-resistant cancer cell population, while Pep R reduced it." (PMID 32708431, 2020). "In cancer spreading, CXCR4 is the main cCKR, whose expression enables cancer cells to migrate and metastasize into the organs that secrete high levels of its ligand, CXCL12." (PMID 32456359, 2020). "According to the clinical studies, combination with other current cancer therapies would be the primary application of plerixafor or other CXCR4 antagonists." (PMID 33363463, 2020). "The array of atypical cancer-regulating functions of CXCR7/ACKR3—when it acted alone or in the context of CXCR4—were discussed in the previous sections of the article, as appropriate." (PMID 32582148, 2020). "Over the past few years, a number of inhibitors of CXCL12/CXCR4 have been identified and currently are in different development stages as potential agents for the treatment of cancers." (PMID 32232002, 2020). "To assess the effects of cancer stage on CXCR4 expression, we analyzed RNA-seq data in n = 1625 CRC patients from the TCGA." (PMID 32110952, 2020). "CXCR4 is a highly conserved receptor expressed on various cell types, including several cancer cells." (PMID 32784743, 2020). "CXCR4 was localized at the cell membrane and/or cytoplasm of cancer cells and its expression was heterogeneous within the tumors, probably in relation to hypoxic and necrotic areas." (PMID 32708431, 2020). "To date, many studies have focused on the detection and possible prognostic significance of CXCR4 as a reliable CSC marker in other cancers." (PMID 31983166, 2020). "Opportunistic cancer cells, however, exploit this signaling axis by elevating their own CXCR4 levels to promote cell proliferation, angiogenesis, and ECM remodeling." (PMID 33521055, 2020). "While CCL14 and XCL1 have shown only good prognostic value, other chemokines such as CCL5, CCL20/CCR6, CCR7, CXCL1, CXCL8, and CXCL12/CXCR4 have consistently played the role of poor prognostic markers in different kinds of cancer." (PMID 31991604, 2020). "CXCR4 is also expressed on putative cancer stem cells populations in various tumors, including renal, prostate and non-small lung cancer, and affects their clonogenicity and spherogenicity, with adverse effects on prognosis." (PMID 32983169, 2020). "For example, cancer cells metastasize to other organs by upregulating the AA-induced surface chemokine CXCR4; thus, CXCR4 on the CTC surface binds to its ligand CXCL12/SDF-1, which is expressed in the early PMN117." (PMID 33203856, 2020). "CXCR4 was overexpressed in many types of human cancers, and its expression was correlated with angiogenesis, metastasis, and prognosis." (PMID 32232002, 2020). "At present, different cancer types have been shown to overexpress C-X-C chemokine receptor type 4 (CXCR4) and to respond to its ligand C-X-C motif chemokine 12 (CXCL12)." (PMID 32260318, 2020). "It is the ligand of CXCR4 expressed on cancer cells and plays an important regulatory role in both cancer initiation, angiogenesis, and metastasis." (PMID 32466591, 2020). "Consistent with this, in recent years genomic findings have provided important insights into the relevance of the CXCL12/CXCR4 axis for pathogenesis, prognostication, and treatment outcome of cancer." (PMID 32784523, 2020). "This study demonstrates that the three anti-CXCR4 scFvs can induce cell apoptosis of the three cancer cell lines by the regulation of apoptosis signaling pathway." (PMID 33392074, 2020). "In solid tumors, CXCL12 can be secreted both by cancer cells and CAFs, playing a role in paracrine or autocrine fashion, through either CXCR4 or CXCR7." (PMID 32784743, 2020). "CXCL12 signaling has also been observed in CXCR4 expressing cancers and is involved in cancer cell invasion and metastasis." (PMID 32316469, 2020).
cancer (continued). "Recently, CQ had been demonstrated to function as an inhibitor of CXCR4 signaling and have an impact on the cancer stem-like phenotype." (PMID 32232002, 2020). "We previously reported that CXCR4 activation by its aberrant promoter demethylation was associated with hypoxia-induced acquisition of EMT and cancer stem cell characteristics in lung cancer." (PMID 32606331, 2020). "CXCR4 and/or CXCR7, with their ligand CXCL12, are associated with many neurological and inflammatory conditions, as well as many cancers." (PMID 32098047, 2020). "This is due to that the cells highly express CXCR4, upon injection, these CXCR4 + cells are attracted into the areas enriched in CSCs or cancer stem niches." (PMID 32588948, 2020). "The CXCL12/CXCR4 axis influences cancer biology, promoting survival, proliferation, and angiogenesis, and plays a pivotal role in directing migration of cancer cells to sites of metastases, making it a prognostic marker and a therapeutic target." (PMID 32260318, 2020). "Our goal was to investigate the anti-cancer actions of matrine, especially its anti-metastasis activities with reference to the CXCR4 signaling axis in various cancer cells." (PMID 32630806, 2020). "CXCL12 expressing organs are a target for CXCR4 positive cancer cells and blocking the CXCL12/CXCR4 interaction using neutralizing antibodies (nAb) significantly inhibits experimental metastases." (PMID 33414786, 2020). "CXCL12, a ligand for CXCR4, is abundantly produced by neighboring stromal cells and activation of CXCR4-expressing cancer cells by CXCL12 leads to enhanced chemotaxis, trans-endothelial migration, and invasion." (PMID 32224910, 2020). "The CXCR4/CXCL12 pathway has substantial literature support that establishes the role of the CXCR4 gene in cancer." (PMID 33092526, 2020). "Cancer cells induce TGF-β-dependent upregulation of C-X-C motif chemokine receptor 4 (CXCR4) on monocytes." (PMID 32943996, 2020). "The interaction between CXCL12 and CXCR4 activates heterotrimeric G proteins, which regulates actin polymerization and cancer cell migration." (PMID 32292657, 2020). "To analyze the effect of CXCR4 on drug sensitivity, we used data from the Genomics of Drug Sensitivity in Cancer database (GDSC)." (PMID 32306562, 2020). "Cancer cells-derived TGF-β upregulates CXCR4 in motile TAMs and guides them towards CXCL12 released by perivascular fibroblasts." (PMID 33096815, 2020). "Cancer cells expressing CXCR4 tend to home to secondary organs where its ligand CXCL12 is actively secreted, mainly by mesenchymal stromal cells." (PMID 32432042, 2020). "HSPA4 targeting IgG activated the HSPA4-binding protein ITGB5 and the downstream Src/NF-κB pathway in cancer cells to promote CXCR4/SDF1α-axis-mediated cancer metastasis." (PMID 32746880, 2020). "CXCR4 is highly expressed in over 20 cancer types, ranging from hematological malignancies to solid tumors." (PMID 33014834, 2020). "Chemokine receptor 4 (CXCR4) is a chemokine receptor that has been found to be overexpressed in various types of cancer, including leukemia, breast cancer, and prostate cancer." (PMID 32306562, 2020). "High levels of CXCR4 have been found in diverse human cancers and play mostly detrimental roles facilitating disease progression and decreasing overall survival." (PMID 33096815, 2020). "CXCR4 is constitutively expressed in various cancers including lung, pancreatic, breast, prostate, and ovarian tumor cells." (PMID 32630806, 2020). "Functional crosstalk between PDGF-BB/PDGFR and stromal-derived growth factor 1α (SDF-1α)/C-X-C motif chemokine receptor 4 (CXCR4) requires enhanced cancer tumorigenesis and metastasis." (PMID 32754598, 2020). "The focus of this mini-review is the emerging role of CXCR4 and its ligands in tissue repair and regeneration, and its relation to cancer cell proliferation." (PMID 32983169, 2020).
cancer (continued). "Overall, the protein levels of CXCR4, Snail1, and A20 correlated the most, and only some cancer cell line-specific aberrations were observed." (PMID 32825729, 2020). "CXCR4 is a member of the C‐X‐C chemokine receptor family, which has been widely investigated in many cancers." (PMID 32306562, 2020). "CXCR4-overexpressing cancer cells are good targets for therapy because of their association with dissemination and relapse in R-CHOP treated DLBCL patients." (PMID 32373205, 2020). "In the present study, we discovered that the CXCR4 levels can affect the resistance of cancer cells to three drugs." (PMID 32306562, 2020). "To investigate the clinical impact of EZH2 and CXCR4 on GBM cancer progression, we analyzed the relationship between their mRNA expression levels and GBM patient prognosis with GEPIA." (PMID 32635336, 2020). "T22-PE24-H6 specifically delivers a de-immunized 24 kDa catalytic domain of Pseudomonas aeruginosa (PE) exotoxin A to the chemokine receptor CXCR4 overexpressing (CXCR4+) cancer cells by interacting with its T22 ligand 11,16." (PMID 32373205, 2020). "Both in vitro and in vivo studies suggest that the expression level of CXCL12/CXCR4 in cancer cells is positively correlated with microvessel density." (PMID 33363463, 2020). "Among them, the role of CXCL12/CXCR4 signaling in cancer and metastasis is well known, and CXCR4 has been often targeted with small molecule-antagonists or short CXCL12-derived peptides to limit the pathological processes of cell migration and invasion." (PMID 33233846, 2020). "For example, CXCR4-positive cancer cells can be recruited to organs with high expression of CXCL12, including liver, lungs, and bone marrow." (PMID 33363463, 2020). "The CXCL12/CXCR4 (C-X-C motif chemokine 12/C-X-C motif chemokine receptor 4) axis plays a crucial role in tumorigenesis, metastasis, and chemoresistance, and therefore is an ideal target for cancer immunotherapy." (PMID 32917034, 2020). "There is increasing evidence suggesting a reciprocal interplay between CXCR4 and NF-κB signaling in fine tuning cancer cellular signaling pathways." (PMID 32432042, 2020). "The functionalization of NP surfaces with the mentioned chemical moieties has been already applied in different drug delivery systems for CXCR4+ cancer cells." (PMID 33233846, 2020). "In this review, we describe the roles of the CXCL12/CXCR4/CXCR7 axis in cancer progression and summarize strategies to develop novel targeted cancer therapies." (PMID 33363463, 2020). "The blockade of the CXCL12/CXCR4 passage has, therefore, emerged as a potential way of targeted cancer therapy." (PMID 32316469, 2020). "While the overexpression of CXCR4/CXCL12 is correlated with the homing of cancer cells to the liver, lung, bone marrow and lymph nodes, the overexpression of the CCR7/CCL21 axis has mainly been related to lymph node metastasis." (PMID 32340161, 2020). "CXCR4 is known to accelerate T cell proliferation and secretion of interferon γ, which facilitates PD-L1 expression in cancer cells and TAMs and also PD-1 expression in CTLs and natural killer cells." (PMID 32972006, 2020). "Other evidence suggests that CXCR4 mediates the interactions between cancer cells and stroma cells by combining with its natural ligand CXCL12." (PMID 32538273, 2020). "CXCR4 is one of several “chemokine” receptors expressed on malignant tumors (including GBM and PCNSL)." (PMID 32239371, 2020). "This suggests that both CXCL12 secretion by CAF-S1 and CXCR4 expression in cancer cells are involved in CAF-S1-mediated EMT initiation in BC cells." (PMID 31964880, 2020). "The chemokine receptors CCR7 and CXCR4, which are expressed by invading cancer cells, bind to secreting chemokines such as CCL21 and CXCL12, to recruit more cancer cells towards lymphatic vessels." (PMID 33172072, 2020).
cancer (continued). "We found in each case that colonocytes from normal colon, adjacent colon and cancers more strongly expressed CXCR4 compared to stromal cells matched to the same tissue (q-value < 0.05)." (PMID 32110952, 2020). "CXCR4/CXCL12 interaction triggers different downstream pathways in cancer cells or in several cells of TME, resulting in diverse biological responses, as angiogenesis, metastasis, proliferation and survival." (PMID 32784743, 2020). "CXCR4 had gained tremendous attention over past decades since it was overexpressed in a multiple cancer types and contributes to their malignant behaviors." (PMID 30940776, 2019). "This is in agreement with a previous study demonstrating that plerixafor was able to reduce CXCR4 in target cancer cells." (PMID 31877673, 2019). "C-X-C chemokine receptor type 4 (CXCR4) and its ligand, stromal cell-derived factor 1 alpha (SDF1α) are known as important chemotactic proteins in cancer metastasis." (PMID 31807240, 2019). "Intriguingly, CXCR4 also plays a critical role in spheroid formation in sphere formation essays used for isolation of cancer stem cell subpopulations, where CXCR4-inhibition drastically reduces sphere size and sphere count in some tumors." (PMID 31810195, 2019). "To determine the functional consequence of CXCR4 and LASP1 on the eIF4F complex, we examined eIF4A-dependent oncogenes commonly associated with cancer." (PMID 31106142, 2019). "C-X-C chemokine receptor type 4 (CXCR4), the receptor for the chemokine stromal cell-derived factor, is one of the members of the chemokine and plays a key role in cancer progression and metastasis." (PMID 31073530, 2019). "The processing of NK cell grafts for cancer immunotherapy often triggers reduced expression of the bone marrow homing chemokine receptor CXCR4, leading to decreased in vitro migration toward the chemokine SDF-1α." (PMID 31231387, 2019). "The development and clinical translation of [68Ga] Pentixafor has substantially promoted the relevance of non-invasive PET imaging of CXCR4 expression in a broad spectrum of diseases, including cancer and inflammation." (PMID 31410585, 2019). "The expression level of CXCR4 in BC correlates with poor prognosis, presence of distant metastasis and reduced overall survival of BC, and other cancer-types patients." (PMID 31027259, 2019). "Aside from being the most commonly deregulated GPCR found in cancer, CXCR4 was also identified as an HIV co-receptor." (PMID 31139626, 2019). "Another alternative yet practical strategy would be pushing DTCs out of their protective niche (e.g., anti-CXCR4) and into a less supportive environment, where they can be targeted and eradicated by anti-cancer drugs." (PMID 31430951, 2019). "In contrast to its normal role in stem cell function during development, CXCR4 is also expressed in various cancers." (PMID 30791675, 2019). "As recent studies have reported CXCR4 to be expressed in the nucleus in some cancers, we performed both cytoplasmic and nuclear staining, with equal weighting given to the two compartments during the analysis." (PMID 31428099, 2019). "SIK3 expression also increases the expression of chemokine CXCL12 and its specific receptor CXCR4 on cancer cells, promoting metastasis." (PMID 31888295, 2019). "Elevated CXCR4 expression has been documented in more than 23 different types of cancers with various origins and has been shown as a poor prognostic biomarker." (PMID 30642351, 2019). "Apparently, the enhanced CXCR4 expression is an autonomous effect of the downregulation of RhoA expression in 4T1 cancer cells." (PMID 31705019, 2019). "We previously demonstrated metapristone (RU486 metabolite) as a cancer metastatic chemopreventive agent targeting SDF-1/CXCR4 axis." (PMID 31151472, 2019). "CXCR4 is overexpressed in more than 23 human cancers and controls metastatic dissemination in the majority of tumors in which is overexpressed." (PMID 31661001, 2019).